DNAAF11 (dynein axonemal assembly factor 11)
Description:
Involved in dynein arm assembly, is important for expression and transporting outer dynein arm (ODA) proteins from the cytoplasm to the cilia. Acts as a crucial component in the formation and motility of spermatozoal flagella.
Synonyms: LRRC6; LRTP; TSLRP; CILD19; tilB
Tractability: Antibody: its Gene Ontology location is reachable by antibodies, with medium confidence.
Gene: Protein-coding gene on chromosome 8 (132,570,416 to 132,675,617, reverse strand). Ensembl gene ENSG00000129295.
Subcellular location: Cytoplasm; Cell projection, cilium; Dynein axonemal particle; Cell projection, cilium, flagellum
Subcellular location (Human Protein Atlas): Mid piece; Principal piece
Gene Ontology:
Molecular function: protein binding
Biological process: axonemal dynein complex assembly; cilium movement; epithelial cilium movement involved in determination of left/right asymmetry; flagellated sperm motility; inner dynein arm assembly; motile cilium assembly; outer dynein arm assembly; protein localization to motile cilium; reproductive system development; cerebrospinal fluid circulation; epithelial cilium movement involved in extracellular fluid movement; establishment of localization in cell; male gonad development; protein localization to cilium
Cellular component: cilium; cytoplasm; cytosol; dynein axonemal particle; apical cytoplasm; extracellular region; motile cilium
Genetic constraint (gnomAD): Loss-of-function variants: 27 observed, 36.59 expected, observed/expected ratio (o/e) 0.74, 90% interval 0.54 to 1.02. The upper end of that interval is the gene's LOEUF score, 1.02, which puts it in group 4 of 6, group 1 being the genes least tolerant of losing a copy. Missense variants: 431 observed, 453.3 expected, observed/expected ratio (o/e) 0.95, 90% interval 0.88 to 1.03. Synonymous variants: 154 observed, 157.1 expected, observed/expected ratio (o/e) 0.98, 90% interval 0.86 to 1.12.
Gene-disease validity (ClinGen):
ClinGen rates the evidence that DNAAF11 causes each of these diseases.
primary ciliary dyskinesia 19 (autosomal recessive): Definitive.
Homologues: Orthologues: chimpanzee DNAAF11 (99% identical), macaque DNAAF11 (97% identical), rabbit DNAAF11 (83% identical), mouse Dnaaf11 (80% identical), dog DNAAF11 (80% identical), pig DNAAF11 (80% identical), rat Dnaaf11 (79% identical), tropical clawed frog dnaaf11 (60% identical), zebrafish dnaaf11 (52% identical), Drosophila melanogaster tilB (38% identical). Paralogues in human: CEP97 (20% identical), LRRC9 (19% identical), LRGUK (18% identical), LRRCC1 (18% identical), DRC3 (17% identical), DNAAF1 (16% identical), LRRC49 (15% identical), LRRC43 (14% identical), LRRIQ3 (12% identical), LRRC46 (12% identical), PPP1R42 (11% identical), LRRC61 (9% identical), and 1 more.
Diseases named in the same sentence as DNAAF11 in open-access papers:
DNAAF11 is named in the same sentence as 15 diseases in open-access papers, as found by Europe PMC text mining. Sharing a sentence is not in itself a finding about the gene and the disease.
DNAAF11 shares sentences with these, for which no sentence is quoted: primary ciliary dyskinesia (7 papers); Infertility (4); male infertility (3); Anxiety (1); asthenospermia (1); autoimmune thyroid disease (1); bronchiectasis (1); cancer (1); chronic maxillary sinusitis (1); ciliopathy (1); cystic kidney (1); Depression (1); Hydrocephalus (1); infection (1); Kidney Cyst (1).